PON1 (paraoxonase 1)
Diseases named in the same sentence as PON1 in open-access papers (continued):
Sharing a sentence is not in itself a finding about the gene and the disease.
type 2 diabetes (58 papers, 2007 to 2026). "In 1995 Ruiz and colleagues reported that in type 2 diabetes the 192R isoenzyme of PON1 was associated with coronary heart disease." (PMID 36873390, 2023). "Both type 1 and type 2 diabetes are associated with decreased PON1 activity and low PON1 activity is related to both macro- and microvascular complications." (PMID 36873390, 2023). "The association of PON1 genetic polymorphisms with insulin sensitivity estimated by the euglycemic hyperinsulinemic clamp was evaluated in Japanese patients with type 2 diabetes." (PMID 33670025, 2021). "This is the first study to report the gene–treatment interaction of the PON1 Q192R polymorphism and statin therapy on insulin secretion among patients with type 2 diabetes." (PMID 29233102, 2017). "Although it is not clear how the mechanism of PON1 affects risk of AD, studies have revealed an association between low PON1 activity, elevated oxidative stress, and increased risk of cardiovascular disease, stroke, type 2 diabetes and dementia." (PMID 28694880, 2017). "In a clinical trial in subjects with type 2 diabetes, increased fruit and vegetable consumption augmented the carotenoid concentrations and PON1 associated with the antioxidant properties of HDL." (PMID 26024295, 2015). "The underlying mechanism of how PON1 Q192R polymorphism and statins interact on insulin secretion in patients with type 2 diabetes remains unclear." (PMID 29233102, 2017). "Among patients with type 2 diabetes and with diseases associated with oxidative stress, PON1 activity was found to be low, probably due to increased oxidative stress inactivating the PON1 enzyme." (PMID 29233102, 2017). "In contrast, in a study on 589 patients (419 Caucasian, 120 South Asian, 50 other) to determine factors which modulate serum PON1 in type 2 diabetes, PON1 activity associated negatively with insulin resistance, triglycerides and 55 M allele; and positively with 192R allele." (PMID 25551104, 2014). "Our study demonstrates an association between PON1 activity and MFR in type 2 diabetic patients though the exact mechanism by which PON1 influences MFR remains unclear." (PMID 22214423, 2011). "Elevated PON1 activity is beneficial for preventingnephropathy in noninsulin-dependent diabetes mellitus (NIDDM) and itsatherosclerotic complications." (PMID 40834279, 2025). "On the contrary, the negative relationship with carbohydrate consumption that we observed coincides with studies linking increases in blood carbohydrates in patients with type 2 diabetes with decreased PON1." (PMID 39199265, 2024). "Furthermore low PON1 may predispose to the development of type 2 diabetes." (PMID 36873390, 2023). "We found a strong correlation between paroxonase-1 and patients’ BMI (rs = 0.823; p = 0.003) and a weak correlation between paraoxonase-1 and type 2 diabetes (rs = 0.608; p = 0.02)." (PMID 36290747, 2022). "In a randomized clinical trial, three-month oral administration of ginger supplementation (3 g/d) in patients with type 2 diabetes, decreased blood glucose concentration, total anti-oxidant capacity, and paraoxonase-1 (PON-1) activity." (PMID 35949312, 2022). "The activity of PON-1 has recently been reported to decrease in step with falling HDL cholesterol levels in type 2 diabetes (T2DM) patients as compared to healthy subjects." (PMID 36463116, 2022). "The correlation between low PON-1 levels in the serum and higher incidence and mortality rates of cardiovascular complications in patients with type 2 diabetes also was suggested." (PMID 36463116, 2022). "Some studies suggest that in diabetes type 2, a diminished paraoxonase 1 (PON1) activity was seen simultaneously to superoxide dismutase (SOD) decrease and a catalase (CAT) increase." (PMID 32911700, 2020). "Decreased PON1 has been found in patients with type 2 diabetes and diabetic macrovascular complications." (PMID 27803713, 2016).
type 2 diabetes (continued). "In another group of patients with type 2 diabetes, administration of 200 mL of pomegranate juice for a shorter period (six weeks) induced similar effects on PON1 activity." (PMID 26024295, 2015). "Measurment of PON1 enzyme activity, evaluation of changes in its performance in patients with type 2 diabetes and managing PJ supplement were the new and positive points of this research." (PMID 23497651, 2012). "The present study was designed to evaluate the effect of PJ on FBS, lipid profiles, lipid oxidation PON1 paraoxonase activity, arylesterase activity of PON1 and their correlation in patients with type 2 diabetes." (PMID 23497651, 2012). "PON1 is low in subjects with Type 1 or Type 2 diabetes, leading to dysfunctional HDL with impaired antioxidant capacity." (PMID 18937674, 2008). "We also report that the likely mechanism behind this effect is the increased glycation of PON1 in people with Type 2 diabetes and those with CHD, which inhibits its activity." (PMID 18937674, 2008). "We have shown for the first time that a significant fraction of PON1 is glycated in vivo and that approximately twice as much PON1 from people with Type 2 diabetes and those with CHD is glycated compared with control subjects." (PMID 18937674, 2008). "In Type 2 diabetes there is an inverse relationship between PON1 activity and circulating oxidized LDL levels, indicative of the major role of PON1 in retarding LDL oxidation." (PMID 18937674, 2008). "The unchanged PON1 and ARE activities are significant, given their associations with increased oxidative stress and various systemic conditions, including neurodegenerative diseases, type 2 diabetes, NAFLD, CKD, and autoimmune disorders." (PMID 39459504, 2024). "Reduced PON1 and ARE activities have been associated with neurodegenerative diseases, such as Alzheimer’s and Parkinson’s, as well as metabolic disorders like type 2 diabetes, where they exacerbate oxidative stress and inflammation." (PMID 39459504, 2024). "Vitamin E was found to improve PON1 activity in patients with type 2 diabetes." (PMID 35889799, 2022). "PON1 activity has been reported to be lower in subjects with type 2 diabetes." (PMID 35889799, 2022). "In our study, we found a correlation between PON1 and type 2 diabetes." (PMID 36290747, 2022). "Similarly, a diet rich in fruit and vegetables has been shown to increase PON-1 activity in type-2 diabetic subjects compared to a Western-style diet." (PMID 35978954, 2022). "An increase in PON1 activity was observed following the daily consumption of a pomegranate beverage (total phenol content of 2600 mg GAE/L of juice) for 4 weeks in 30 patients with type 2 diabetes." (PMID 30544803, 2018). "Lower PON1 activity was associated with carotid arteriosclerosis and cerebral atherosclerosis in stroke patients, and was reported as a risk factor for CVD in systemic lupus patients and CAD in type 2 diabetes in North-West Indians." (PMID 25551104, 2014). "Thus, we aimed at assessing the relation of PON1 genotype and activity to myocardial blood flow and myocardial flow reserve in a population of type 2 diabetic patients using 82Rb cardiac positron emission tomography/computed tomography [PET/CT]." (PMID 22214423, 2011). "HDL-associated MPO was negatively correlated with PON1 activity in patients with type 2 diabetes and coexisting CVD, non-diabetic patients with chronic ischemic heart disease, and patients with acute coronary syndromes; the results similar to that observed by us in RA patients." (PMID 32967340, 2020). "The amount of glycated PON1 in serum increased from 7.5% in control subjects to 12% in those with CHD and 17% in those with Type 2 diabetes (both P < 0.01)." (PMID 18937674, 2008). "PON1 was glycated in vivo: (7.5% control, 12% CHD, 17% Type 2 diabetes P < 0.01) with QQ isoforms most glycated." (PMID 18937674, 2008).
type 2 diabetes (continued). "Compared with the control subjects, both the groups with Type 2 diabetes and CHD had higher serum triglycerides and significantly lower PON1 activity and concentration." (PMID 18937674, 2008). "It is therefore possible that the increased in vivo glycation of PON1 leads to its glyoxidation and is responsible for the derangement of membrane hydroperoxide metabolism found in HDL from people with Type 2 diabetes and those with CHD." (PMID 18937674, 2008). "Nevertheless, rosiglitazone,a PPARγ agonist that can improve insulin sensitivity and glycemic control inpatients with type 2 diabetes, was found to increase PON1 activity, although therewas no significant change in the serum PON1 concentration." (PMID 40834279, 2025). "In conclusion, in people with Type 2 diabetes and those with CHD, PON1 is heavily glycated in vivo." (PMID 18937674, 2008). "In a randomized controlled trial on subjects with type 2 diabetes, increasing fruit and vegetable intake for 8 weeks resulted in a rise in carotenoids (α-carotene, β-cryptoxanthin, lutein, lycopene) in serum, HDL2, and HDL3, which was accompanied by an increase in PON1 activity in serum and HDL3." (PMID 35889799, 2022). "In type 2 diabetes mellitus conditions (T2DM), HDL anti-inflammatory capacity is impaired due to decreased PON-1 activity." (PMID 29515356, 2018). "The potential of a high fruit and vegetable diet rich in carotenoids to increase PON1 activity is especially valuable, as PON1 improves the anti-atherogenic mechanisms of HDL and helps to fight the potential negative complications of type 2 diabetes." (PMID 35889799, 2022).
Stroke (44 papers, 2006 to 2025). Sudden impairment of blood flow to a part of the brain due to occlusion or rupture of an artery to the brain. "Carotid atherosclerosis can be a cause of stroke, and PON1 is implicated in intima media thickness, but some studies showed a link between them only in the 55LL genotype." (PMID 38474211, 2024). "The presence of the R allele of the Q192R PON1 polymorphism seems to potentiate this risk for stroke." (PMID 38397934, 2024). "In contrast, low PON1 activity predicted a greater incidence of MI and stroke, all-cause mortality, and MACEs." (PMID 37175471, 2023). "HDL-associated PAF-AH activity, PON-1 activity, and ChE were lower in stroke patients than in control subjects, although only PAF-AH and PON-1 reached statistical significance." (PMID 36829998, 2023). "Each standard deviation increment in vegetable intake was associated with a 40% reduction in the risk of stroke among carriers of the PON1 rs662 AA genotype." (PMID 35987633, 2022). "In the same study, a significant interaction between vegetable intake and the PON1 rs662 variant on the risk of stroke was found." (PMID 35987633, 2022). "For example, paraoxonase 1 (PON1) is a HDL-associated protein mediating HDL functionality that has been negatively correlated with unfavorable outcome in stroke patients." (PMID 33809504, 2021). "Among the identified proteins, PON1 seems to be best validated in human stroke patients, especially for several gene polymorphisms leading to higher susceptibility for IS." (PMID 34975707, 2021). "Determining the association between the alleles of PON1 and DM-related complications including stroke is an interesting scope of future research." (PMID 32872672, 2020). "Previous studies have shown that stroke patients undergo inflammation and oxidative stress, associated with defective HDLs and low PON1 activity." (PMID 32708891, 2020). "In this context, the PON1 genotype has been associated with cardiovascular diseases, including stroke." (PMID 30410197, 2018). "Both rs705381 and rs854571 polymorphisms located in the promoter region of PON1 were associated with stroke, which was consistent with previous findings." (PMID 23356507, 2013). "Recently, we reported that L55 M and C-2033T alleles of the Paraoxonase 1 (PON1) gene, which were correlated with stroke in an East Asian population, were associated with the Dampness-Phlegm pattern among Korean stroke patients." (PMID 22927882, 2012). "For example, polymorphisms in the paraoxonase 1 (PON1) gene, which is involved in preventing oxidative damage to lipids, have been associated with both increased and decreased stroke risk in different ethnic groups, highlighting the complexity of genetic–environment interactions." (PMID 40863347, 2025). "Additionally, decreased serum PON-1 activity has been shown to predict an increased risk of long-term detrimental CVD outcomes (stroke, heart attack, or death) in CKD patients." (PMID 36140402, 2022). "The Q192R allele of PON1 seems to be the most promising predictor of stroke." (PMID 32872672, 2020). "In relation to the antioxidant capacity of HDLs, we observed that HDL-associated PON1 was significantly decreased in stroke patients with unfavorable outcomes, which may potentially reduce their ability to protect LDL from oxidation." (PMID 32708891, 2020). "Circulating paraoxonase-1, a potential clinically useful biomarker for IS diagnosis, has been reported to inhibit the progression of atherosclerosis and lower the risk of stroke by protecting lipoproteins against oxidative modification." (PMID 29215590, 2017). "In addition, PON-1 polymorphisms are associated with a differential sensitivity to salt, which is high in Japanese cuisine, and salt intake contributes to hypertension and risk for stroke." (PMID 39765763, 2024). "Furthermore, we observed an association between PON1 activity history of stroke and splenectomy." (PMID 37137941, 2023).
Stroke (continued). "The protective effect of -162 T polymorphism on total stroke and ischemic stroke was also consistent with previous observations which suggested that NF-1, a ubiquitous nuclear factor and a transcriptional activator, has a binding site on PON1 if allele A appears at −162." (PMID 23356507, 2013). "Regarding stroke cases, polymorphisms in some genes such as MTHFR, eNOS, ACE, AGT, ApoE, PON1, PDE4D were associated with a higher risk of ischemic stroke." (PMID 38478535, 2024). "PON1 activity is reduced in stroke patients, which significantly correlates inversely with carotid and cerebral atherosclerosis." (PMID 38397934, 2024). "The effects of the PON1 Q192R gene on the outcome of a stroke are partially mediated by their effect on two distinct catalytic sites, specifically CMPAase vs arylesterase (AREase) activities." (PMID 36671047, 2023). "We have found that SCD individuals with previous stroke history had lower PON1 activity, while those who underwent splenectomy exhibited higher PON1 activity." (PMID 37137941, 2023). "In performed subgroup analysis, an association of PON1 and PON3 methylation levels with stroke was found only in males." (PMID 33670025, 2021). "Variants in PON1 previously have been associated with serum HDL and LDL cholesterol levels, and with increased risk for stroke." (PMID 20406466, 2010). "In this context, it is not clear why the low paraoxonase and arylesterase activities of PON1 were associated with nonfatal stroke and MI, but the PON1-192QQ genotype was not." (PMID 39594433, 2024). "Moreover, 34.7% of the variance in baseline score of the National Institutes of Health Stroke Scale (NIHSS) score was explained by PON1 status and HDL-cholesterol and hypertension." (PMID 36671047, 2023). "The CpGs at +15 and +241 bp in the PON1 promoter were related to weight, waist circumference, and energy intake in the group of patients without stoke, and an interaction was observed between the energy intake and total PON1 promoter methylation in the prediction of stroke condition (p = 0.017)." (PMID 35453382, 2022). "Interestingly, HDL isolated up to 4.5 h after stroke are larger and contain less apoA-I and PON1 but more α1antitrypsin (AAT) and MPO." (PMID 33924941, 2021). "A negative correlation between PON1 activity and the risk of stroke was observed, likely due to the antiatherogenic properties of PON1." (PMID 32872672, 2020). "The polymorphisms Q192R and L55M, and the paraoxonase activity of PON1 are not risk factors for atherothrombotic stroke according to the results of this study." (PMID 30410197, 2018). "However, it is unknown if the PON1 Q192R gene may influence the outcome of a stroke by influencing antioxidant defenses, lipid peroxidation, neurotoxicity and stroke volume." (PMID 36671047, 2023). "Moreover, data suggest PON1 activity as a potential biomarker related to stroke and splenectomy." (PMID 37137941, 2023). "Thus, the pronounced oxidative damage found in HDL isolated from stroke patients could also contribute to the observed decrease in PON1 activity." (PMID 36901834, 2023). "Some prospective studies have demonstrated that higher HDL levels are associated with lower stroke risk in long-term observation, and an increase in of oxidative stress in HDL particles from patients after ischemic stroke is linked to decreased anti-oxidant enzyme paraoxonase 1 (PON-1) activity." (PMID 35054033, 2022). "The PON1 Q192R gene has multiple effects on stroke outcome which are mediated by its effects on lipid peroxidation, antioxidant defenses, neurotoxicity, DWI stroke volume and FLAIR signal intensity." (PMID 36671047, 2023). "The pathogenesis of VaD is complex and is the result of a variety of cardiovascular or genetic risk factors associated with Apolipoprotein E (APOE), angiotensin I converting enzyme (ACE), paraoxonase 1 (PON1), or presenilin 1 (PSEN1) genes, or due to stroke." (PMID 34938197, 2021).
Stroke (continued). "Decreased content in PON1, increased content of AAT, and reduced anti-inflammatory functions of HDL are preserved three months after stroke." (PMID 33924941, 2021). "Based on our data, we suggest that CPN2, FXII, PLG, MASP1, APCS, PON1, and CA1 for IS and FBLN1 and GRN for ICH should be further scientifically pursued as potential stroke blood biomarkers." (PMID 34975707, 2021). "From among 75 genes regarded as stroke–responsible, the miR-SNPs were detected in 13 and, finally, the miR-SNP rs3735590 at the 3′ UTR of PON1 gene was identified by using the miRNA arrays." (PMID 33670025, 2021). "Both PON1 and AAT protein levels were significantly different in HDLs from stroke patients compared with HDLs from healthy donors." (PMID 32708891, 2020). "A negative association has previously been demonstrated between SNPs in the coding region of PON1 and PON2, and the development of stroke." (PMID 23356507, 2013). "Regarding analyses between clinical manifestations and PON1 activity in SCD patients, we observed a significant decrease in PON1 activity in those with previous stroke history or who did not undergo splenectomy." (PMID 37137941, 2023). "However, it cannot be ruled out that this alteration in PON1 levels is the result of a redox imbalance following stroke." (PMID 36901834, 2023).